S100A9 (S100 calcium binding protein A9)
Diseases named in the same sentence as S100A9 in open-access papers (continued):
Sharing a sentence is not in itself a finding about the gene and the disease.
breast carcinoma (continued). "En_CXCR4, En_S100A9, and En_PPP1R1B were specifically highly expressed in the angiogenic group, suggesting that these marker genes may be new targets for anti-angiogenic therapy and forebode breast cancer prognosis in the future." (PMID 37626402, 2023). "Our findings highlight a unique oncogenic breadth of this pathway, especially sEVs produced by invasive breast cancer cells in hypoxia to globally reprogram a normal mammary epithelium while also introducing systemic immunosuppression via myeloid cell release of the S100A9 alarmin." (PMID 36892943, 2023). "In addition, evaluation of S100A8 and S100A9 has been limited to only breast cancer." (PMID 36284356, 2022). "Importantly, the AhR has been demonstrated to regulate the expression of immune-regulatory markers including Arg1, IDO, IL-10, COX-2, C/EBPβ, and S100A9, which are critical factors in the pathogenesis of breast cancer." (PMID 36588678, 2022). "For example, knowledge that S100A8 and S100A9 are crucial for the generation of the pre-metastatic niche in the lung led to the development of S100A9 specific single photon emission computed tomography (SPECT) whole body imaging which has been tested in a pre-clinical breast cancer metastasis model." (PMID 31071959, 2019). "To further explore the clinical significance of S100A8/A9 and DACH1 levels in breast cancer, we performed a combined analysis using the IHC staining scores of S100A8, S100A9, and DACH1." (PMID 38093319, 2023). "Survival analysis demonstrated that elevated S100A8/A9 predicted a poorer prognosis for breast cancer patients, and the mean expression of S100A8 and S100A9 independently served as a prognostic factor for overall survival in breast cancer patients." (PMID 38093319, 2023). "For the scenario 1 in the cohort 1 dataset, analysis of Normal vs. Breast Cancer samples produced model 1 which incorporated S100A8, S100A9, and breast density as the predictors." (PMID 36284356, 2022). "Analysis of Normal & Call-back vs. Breast Cancer samples produced a model 3 with S100A8 and S100A9 as the predictors." (PMID 36284356, 2022). "Further, MDSCs and TANs express high levels of S100A9 and the immunosuppressive enzymes IDO and arginase 1 (Arg1) which are specific for their immune-suppressive activity in TME of breast cancer." (PMID 36588678, 2022). "Analysis of Call-back vs. Breast Cancer samples produced model 2 which incorporated S100A8, S100A9, and age as the predictors." (PMID 36284356, 2022). "Research on protein basis showed that high S100A/S100A9 expression could serve as an indicator for clinical outcomes in lung cancer, and this single-cell transcriptome study demonstrated significant expressions of these proteins in breast cancer lymph node metastases." (PMID 36148946, 2022). "The current work utilizes S100A9‐targeted CPMV as both an immunoprophylaxis and therapeutic approach against metastatic models of breast cancer and melanoma." (PMID 34519180, 2021). "Youden index analysis also showed that five proteins including S100A9, SRSF6, THBS1, CUL4A, and CANX can accurately diagnose breast cancer patients at the metastatic and primary stages from healthy individuals." (PMID 32793473, 2020). "Our findings revealed increased levels of S100A9 and CUL4A leading to a reduced overall and relapse-free survival rate in breast cancer patients." (PMID 32793473, 2020). "The identified PBMC biomarkers (TMSB4X, HSPA4, S100A9, SRSF6, THBS1, CUL4A, and CANX) were significantly upregulated in the breast cancer patients at the metastatic stage compared to both the primary stage and healthy individuals (p < 0.001)." (PMID 32793473, 2020). "One study conducted on breast cancer cell line showed that extracellular treatments with S100A8 and S100A9 proteins induce cell proliferation, while intracellular recombinant expression of S100A8 and S100A9 block cancer cells grow." (PMID 25298751, 2014).
breast carcinoma (continued). "In a breast cancer mouse model, plasma samples from preclinical tumor-bearing mice compared with control mice show an upregulated protein expression of S100A8, S100A9, and LCN2." (PMID 22559235, 2012). "Additionally, it was found that S100A9 levels, as determined by liquid biopsy, were a significant predictor of radiation response in a cohort of brain-metastatic NSCLC, breast cancer, and melanoma patients." (PMID 39695143, 2024). "Here, we analyzed the correlation among S100A8, S100A9, and DACH1 mRNA expression in breast cancer." (PMID 38093319, 2023). "Similarly, the result of Kaplan-Meier survival analysis showed that high S100A9 and S100A8/A9 mean value were unfavorable factors for the OS of breast cancer patients." (PMID 38093319, 2023). "In addition, analysis based on TCGA breast cancer RNA-seq datasets showed the same trend that S100A8 and S100A9 mRNA was upregulated in ER-, PR-, and Her2 + patients (P < 0.0001)." (PMID 38093319, 2023). "Altogether, our CyTOF and DIA analyses identified S100A9 as the top intrinsic factor which may be responsible for the formation and dynamic changes of TME to benefit breast cancer progression." (PMID 35304461, 2022). "In the analysis of human database, we found that S100A9 expression level was positively correlated with human breast cancer development stages and Pearson correlation analysis revealed a negative correlation between BRCA1 and S100A9 in breast cancer patients." (PMID 35304461, 2022). "Thus, we tested the efficacy of combination treatment with a chemical inhibitor of S100A9 or CXCL12 and αPD1 in BRCA1-MT mice, and found the treatment significantly inhibited mammary tumor growth, recurrence, and metastasis." (PMID 35304461, 2022). "The major transcriptional effects of DMHCA were linked to transrepression of a network of LXR-responsive genes, including PTGS2, S100A9, SPP1, CD14, CCL5 and ANXA1, which are overexpressed in MDSC and in a significant proportion of breast cancers, where they denote poor survival." (PMID 33780491, 2021). "S100A8 and S100A9 showed distinct up-regulation in the co-cultured MCF10A cells and their microenvironmental upregulation was also observed in the orthotropic xenograft of syngeneic mouse mammary tumors." (PMID 33446797, 2021). "Finally, in silico analysis confirmed that a gene set consisting of S100A9, SRSF6, THBS1, CUL4A, and CANX were found to provide an insight for the identification of metastasis in breast cancer patients." (PMID 32793473, 2020). "Thus, down-regulation of S100A8 and S100A9 genes by 4-OH-TAM can be related to the inhibition of the invasive and migratory phenotypes of human breast cancer cells, particularly in ER--breast cancer cells." (PMID 29416786, 2018). "Thus the conclusion that S100A9, S100A11 and S100P correlated to worse outcome in breast cancer patients seems plausible, and it’s required to further study the precise prognostic significance of them in breast cancer." (PMID 28051137, 2017). "For example, miR-196a has been studied for its oncogenic roles in glioblastoma, pancreatic adenocarcinoma, breast cancer, oesophageal adenocarcinoma, and colorectal cancer, and shown to target HOX family genes (HOXA7, HoxB7, HOXC8, HOXB8, HOXD8), ERG, HMGA2, ANXA1, S100A9, SPRR2C, KRTS." (PMID 24621885, 2014). "A few recent studies have reported that women with breast cancer who experience greater distress or have lower social support and social wellbeing (SWB) displayed greater inflammatory signaling and poorer clinical outcomes as well as greater S100A9/S100A9 levels." (PMID 39830522, 2024). "To further elucidate the specific cell–cell communication by S100A8/S100A9 signaling in the tumor ecosystem, we analyzed RAGE and TLR4 signaling via measuring ligand and receptor expression in different cell types using single-cell RNA-seq data from two breast cancer metastases." (PMID 35440136, 2022).
breast carcinoma (continued). "Concentrations of S100A8 and S100A9 were found to be elevated in breast cancer (mean concentration of 2997.17 pg/ml for S100A8 and 5729.19 pg/ml for S100A9) compared with the control group (mean concentration of 1003.92 pg/ml for S100A8 and 2107.35 pg/ml S100A9)." (PMID 35471994, 2022). "High level of S100A9 but not that of S100A8 was found to be associated with loss of ER and the poor overall survival of breast cancer patients and to be involved in the poor prognosis of Her2+/basal-like subtypes of breast cancer." (PMID 29416786, 2018). "Finally, a gene set consisting of S100A9, SRSF6, THBS1, CUL4A, and CANX were introduced as potential candidate genes helpful in distinguishing metastatic from non-metastatic breast cancer patients." (PMID 32793473, 2020).
COVID-19 (77 papers, 2020 to 2025). A disease caused by infection with severe acute respiratory syndrome coronavirus 2. "The current study found that S100A9 is a serological biomarker for risk assessment in COVID-19 patients." (PMID 35885892, 2022). "Furthermore, recent studies have also shown that S100A9 is associated with poor outcomes in coronavirus disease 2019 (COVID-19)-induced pneumonia." (PMID 33549095, 2021). "However, no research has yet investigated the association between serum and faecal levels of S100A8/S100A9 in COVID-19." (PMID 34753964, 2021). "Elevated mRNA expression of S100A6, S100A8, S100A9, and S100P, have been identified in the nasal swabs of COVID-19 patients." (PMID 41164170, 2025). "S100A8 and S100A9 show the highest hubness in the networks of the four COVID-19 severity groups, particularly the genes that are regulated by a large number of parent genes." (PMID 40362649, 2025). "Collectively, we suggest that controlling CXCL8 and S100A9 and the main players HLA class I is crucial to uncover the immune disease-related mechanisms of COVID-19 severity." (PMID 40580453, 2025). "In the context of COVID-19, the induction of neutrophils by S100A9 was shown to be effectively blocked by Paquinimod." (PMID 39497822, 2024). "S100A9 was upregulated only in adults with severe COVID-19, while upregulation of TNFSF10 (TRAIL) was correlated with p-PB, indicating more robust inflammation in these groups." (PMID 37638019, 2023). "In summary, SPDEF and ELF3 were shared between goblet and squamous cells in severe COVID-19, and S100A9 was co-upregulated." (PMID 37936693, 2023). "The alarmins S100A8/S100A9 are ranked among the top DEGs increased in progressive vs stable monocytes, as also shown by recent scRNA-seq COVID-19 studies, and as observed in SARS-CoV infection." (PMID 35064122, 2022). "A recent study reported that immature neutrophils with elevated calprotectin S100A8/S100A9 plasma levels can be used as robust biomarkers of COVID-19 severity." (PMID 35903092, 2022). "Levels of the inflammasome cytokine IL1B, the neutrophil chemotaxis factor CXCL8, and alarmins S100A8 and S100A9 were comparably elevated in KD and severe COVID-19 compared to FC and HC, respectively." (PMID 36159873, 2022). "Among the PIRAT-coexpressed genes were the PU.1-dependent alarmins S100A8 and S100A9, which play a key role in COVID-19 (5, –7, 23, 24)." (PMID 35998224, 2022). "Only levels of IL1B, neutrophil chemotactic CXCL8, and alarmins S100A8/S100A9 were comparably elevated in KD and COVID-19 compared to their respective controls." (PMID 36159873, 2022). "Collectively, PIRAT down-regulation and LUCAT1 up-regulation in monocytes in this model fuels the expression of S100A8 and S100A9, which contribute to myeloid imbalances during severe COVID-19." (PMID 35998224, 2022). "The inflammatory mediator of EN-RAGE encoded by S100A12 was significantly correlated with COVID-19, and S100A8, S100A9, IRF3, IFI6, IFITM1, and IFITM3 have been reported to elicit autoinflammatory and autoimmune conditions in response to SARS-CoV-2 infection." (PMID 35172892, 2022). "Severe COVID-19 is associated with a high circulating level of calprotectin, the S100A8/S100A9 alarmin heterodimer." (PMID 35644124, 2022). "Classical monocytes also transcribed several genes encoding for the S100 protein family, such as S100A4, S100A8, S100A9, and S100A12, which were recently implicated in COVID-19." (PMID 34424199, 2021). "In a clinical setting involving 48 subjects, the expression of TLR4 and its downstream signaling molecules as well as S100A9 (TLR4 ligand) were significantly upregulated in PBMCs from severe COVID-19 patients as compared to those from healthy controls." (PMID 34458281, 2021). "For all neutrophil markers except IL-8, levels further increased as COVID-19 severity increased, and a progressive, stepwise increase was observed for S100A9 and IL-16." (PMID 33232303, 2021).
COVID-19 (continued). "For example, inflammatory genes including S100A8 and S100A9 were upregulated in COVID-19 compared to healthy donors." (PMID 34108966, 2021). "Furthermore, S100A8 and S100A9 are also considered crucial therapeutic targets for inflammatory response to COVID-19." (PMID 40362649, 2025). "Additionally, the levels of S100A4, S100A9, and S100A10 have been shown to influence inflammation and disease severity, associating them with ALI and reduced lymphocyte counts in COVID-19 patients." (PMID 41164170, 2025). "Thus, uncovering novel treatment approaches targeting the molecular system of ACKR2, S100A8, and S100A9 for COVID-19 is a future research step in our study." (PMID 40362649, 2025). "Among these genes, S100A9 has already been suggested as a potential biomarker of COVID-19 severity." (PMID 38262689, 2024). "Furthermore, recent studies have also indicated an association between S100A9 and COVID-19-induced pneumonia as well as ARDS, suggesting a potential significant impact of S100A9 on ARDS induced by COVID-19." (PMID 39686985, 2024). "Furthermore, S100A9 expression increases in severe COVID-19 patients before 10 d of symptom onset, suggesting that this increase is not just a consequence of prolonged inflammation." (PMID 38262689, 2024). "Furthermore, we demonstrated the important role of some inflammatory genes (such as S100A8 and S100A9) in the pathogenesis of COVID-19 and found that regulators of these critical genes can be unique to cell types and conditions." (PMID 37936693, 2023). "Moreover, proteins related to the inflammatory response and tissue injury, including proteins S100-A8, S100-A9, serum amyloid A-1, serum amyloid A-2, and immunoglobulins, were significantly increased in the COVID-19 groups, resulting from SARS-CoV-2 infection." (PMID 35937696, 2022). "Clinical studies revealed high S100A8 and S100A9 serum concentrations as the best predictive biomarkers for critical COVID-19 cases and mortality, indicating that these endogenous ligands of TLR4 amplify also the aberrant innate anti-viral response during SARS-CoV-2 infection." (PMID 35741108, 2022). "However, the exact role of S100A8 and S100A9 during this infection is still under investigation and it has still to be clarified how both S100A8/S100A9 mechanistically contribute to the outcome of COVID-19." (PMID 35741108, 2022). "Also, a Ca2+ binding protein S100A9, which induces inflammatory cytokine secretion and immune cell migration during inflammation 31, was higher expressed COVID-19-children." (PMID 34335977, 2021). "As calprotectin can regulate the production of TNF-α and CXCL8 and promote NF-κB activation, elevated levels of the S100A8/S100A9 heterodimer may trigger a harmful hyperinflammatory loop in patients with severe COVID-19." (PMID 34471261, 2021). "Recent studies have reported that in COVID-19 patients the levels S100A9 are increased, suggesting that S100A9 may also play an important role in COVID-19-induced lung injury." (PMID 33549095, 2021). "Single cell RNA sequencing analyses showed the increased presence of dysfunctional neutrophils expressing S100A8, S100A9, DEFA3 and DEFA4 genes in the PBMCs of severe COVID-19 patients suggesting association of the phenotypic alterations in neutrophils with disease severity." (PMID 34746027, 2021). "Our analysis revealed that severe COVID-19 patients exhibit overexpression of genes coding for proteins of extracellular exosomes, endomembrane system, and neutrophil granules (e.g., S100A9, LY96, and RAB1B), which may play an essential role in the cellular response to infection." (PMID 38262689, 2024). "In addition, we note specific upregulation of alarmins S100A8/S100A9 (i.e., calprotectin) among epithelial cells in the severe COVID-19 group compared to mild or moderate and control counterparts, and even higher expression of S100A9 within SARS-CoV-2 RNA+ cells from those same individuals." (PMID 34352228, 2021).